PPARG (peroxisome proliferator activated receptor gamma)
Diseases named in the same sentence as PPARG in open-access papers (continued):
Sharing a sentence is not in itself a finding about the gene and the disease.
colitis (204 papers, 2005 to 2026). Inflammation of the colon. "In a different murine study, PPARγ-deficient T cells in mice with DSS-induced experimental colitis exacerbated disease onset and weight loss." (PMID 39451206, 2024). "In a murine model, DSS-induced colitis was exacerbated by PPARγ-deficient macrophages—not only in the disease activity index but also in histological samples." (PMID 39451206, 2024). "Genetic ablation of PPARγ results in increased susceptibility to experimental colitis in mice, supporting its anti-inflammatory properties." (PMID 37118698, 2023). "PPARγ is further involved in Treg homeostasis, as PPARγ deficiency led to reduced Treg recruitment in a colitis model, whereas PPARγ activation increased the induction of Tregs." (PMID 35954274, 2022). "Increased transcriptional activity of PPARγ was linked to decreased intestinal inflammation in DSS-induced colitis mice." (PMID 34997010, 2022). "Rosiglitazone, pioglitazone, troglitazone and AS002, known PPARγ agonists, have demonstrated protection and recovery from pathogenic inflammation in colitis mouse models." (PMID 35003101, 2021). "Similar deficiencies in PPARγ expression were observed in macrophages of the lamina propria of DSS-induced colitis mice." (PMID 32536865, 2020). "This study aimed to investigate biological roles of pioglitazone in relieving colitis-associated pain hypersensitivity by a PPARγ tight junction protein-dependent mechanism during the course of dextran sodium sulfate (DSS)-induced intestinal inflammation." (PMID 31989391, 2020). "IEC-specific PPARγ KO mice have increased susceptibility to dextran sodium sulfate- (DSS-) induced colitis." (PMID 30804707, 2019). "In this study, dextran sulfate sodium (DSS)-induced colitis was established in mice to evaluate the effect of bergenin, and the underlying mechanisms were explored from the angle of PPARγ-dependence." (PMID 29375382, 2017). "Conditional knock-out mice in which PPARγ expression is selectively ablated in CECs demonstrate an increased susceptibility to DSS-induced colitis." (PMID 28928735, 2017). "Genetic ablation of PPARγ has been reported to increase susceptibility to experimental colitis in rodents." (PMID 25969456, 2016). "PPARγ-deficient T cell animal studies have demonstrated that PPARγ-deficient Treg cells show an impaired ability to regulate effector T cell functions, leading to the development of colitis." (PMID 27548145, 2016). "Loss of function studies have shown that mice that are heterozygous deficient for PPARγ are more susceptible to inflammation from intestinal ischemia/reperfusion injury and colitis." (PMID 26713087, 2015). "Experimental data support the modeling-derived prediction and demonstrate that the loss of PPARγ enhances a proinflammatory response characterized by Th17 in colitis-induced mice." (PMID 23592971, 2013). "Specifically, we applied mathematical and computational modeling approaches in combination with mouse challenge studies to study the mechanisms underlying the interactions between PPARγ activity and miRNA-146b to regulate colitis during C. difficile infection." (PMID 23071818, 2012). "Probiotic administration attenuated development of signs and symptoms of colitis, reduced colonic expression of TNFα, IL-6 and IFNγ and reserved colonic downregulation of PPARγ, PXR and FXR caused by TNBS." (PMID 21829567, 2011). "In fact, they also showed that PPARγ deficiency in Tregs impairs the ability of Tregs to prevent T-cell transfer-induced colitis." (PMID 20885923, 2010). "Recent studies elaborated on thesefindings by showing that mice deficient in PPARγ expression in epithelial cells andmacrophages displayed increased proinflammatory gene expression andsusceptibility to DSS colitis." (PMID 18615192, 2008). "Conversely, enhanced susceptibility to colitis was observed in mice with reduced PPARγ levels or activity." (PMID 19125181, 2008).
colitis (continued). "Most likely, however, the lack oftherapeutic efficacy of thiazolidinediones during active colitis can beexplained by a loss of PPARγ expression and/or activity thatcoincides with the level of inflammation." (PMID 18615192, 2008). "In another animal study, researchers investigated the role of PPARγ in intestinal epithelial cells (IECs) in DSS-induced colitis in mice; they found that intestinal epithelial lesions became more severe in PPARγ-deficient mice with a mixed FVB/C57BL/6 genetic background." (PMID 39451206, 2024). "However, further intensive studies are needed to reveal the molecular mechanisms underlying the direct link between TDAG51 and PPARγ in the regulation of inflammatory mediator production in DSS-induced colitis model mice." (PMID 36450854, 2022). "PPARγ expression loss was observed in lamina propria macrophages of DSS-induced colitis mice." (PMID 35200626, 2022). "The PPARγ-tight junction protein signaling might be a potential therapeutic target for the treatment of colitis-associated chronic pain." (PMID 31989391, 2020). "We proposed that the PPARγ tight junction protein signaling might be a potential therapeutic target for the treatment of colitis-associated chronic pain." (PMID 31989391, 2020). "Consequently, PPARγ KO mice show increased susceptibility to infection whereas, mice specifically deficient in colonic PPARγ exhibit more acute symptoms of infectious colitis and are resistant to colitis therapy using conjugated linoleic acid." (PMID 33198317, 2020). "Moreover, PPARγ+/− heterozygous mice exhibit increased susceptibility to experimentally induced colitis, indicating PPARγ's involvement in maintaining gut homeostasis." (PMID 24465207, 2014). "Illustrating the close ties between PPARγ and IBD, mice with targeted disruption of the Pparγ gene in intestinal epithelial cells displayed increased susceptibility to dextran sodium sulfate-induced colitis as well as higher mRNA levels of proinflammatory markers in the colon." (PMID 23577023, 2013). "In addition, the deficiency of PPARγ in nTreg cells impairs their ability to prevent effector T cell-induced colitis following transfer of naïve CD4+ T cells into SCID recipients." (PMID 23592971, 2013). "Therefore, the loss of PPARγ in immune and epithelial cells impairs the ability of punicic acid to ameliorate experimental colitis." (PMID 23737845, 2013). "Moreover, mice with a targeted deletion of PPARγ in epithelial cells, macrophages or T cells display increased pro-inflammatory gene expression and susceptibility to colitis." (PMID 23071818, 2012). "UC patients seem to have reduced levels of PPARγ in their colonic epithelium and similar deficiencies were observed in colitis mouse models, but only in macrophages of the lamina propria; confirming the beneficial effects of PPARγ agonists on the attenuation of colon inflammation." (PMID 22662201, 2012). "In conclusion, our data indicates that miRNA-146b and PPARγ activation may be implicated in the regulation of Th17 responses and colitis in C. difficile-infected mice." (PMID 23071818, 2012). "Therefore, ESA was effective in ameliorating disease-associated phenotypes in mice with DSS colitis through a PPARγ-dependent mechanism." (PMID 21904603, 2011). "Moreover, PGJ2 weakens the inhibition of advanced glycation end products (AGEs) on Treg function, and adoptive transfer of PPARγ-deficient Treg cells has a significantly weaker effect than wild-type cells on the prevention and treatment of colitis in SCID mice." (PMID 35392915, 2022). "Pioglitazone ameliorates DSS‐induced colitis and attenuates colitis‐associated mechanical hyperalgesia, with improving integrity of the intestinal mucosal barrier by directly upregulating tight junction protein ZO‐1 through the PPARγ‐tight junction protein signaling." (PMID 34523246, 2021). "Nevertheless, potential functions of PPARγ in the colitis-associated hyperalgesia remain unclear." (PMID 31989391, 2020).
colitis (continued). "Furthermore, disruption of the PPARγ pathway by microRNA-146b may be implicated in the regulation of Th17 responses and colitis in Clostridium difficile-infected mice, and PPARγ tightly controls the plasticity of Th17 cells towards an iTreg phenotype." (PMID 24039925, 2013). "We further demonstrated that exogenous IBN supplementation effectively alleviated colitis symptoms in mice and enhanced gut barrier function via activation of the peroxisome proliferator-activated receptor γ (PPARγ) pathway." (PMID 40948937, 2025). "It was observed that treatment with IBN in DSS-induced colitis mice increased PPARγ expression at gene and protein levels." (PMID 40948937, 2025). "A diet with a low n-6/n-3 PUFA ratio was more effective in reducing inflammation in murine models of colitis via PPARγ activation." (PMID 40732220, 2025). "Preclinical:: FABP5 inhibitor, PPARγ agonists ameliorate colitis.Clinical:: T cell lipid raft abnormalities in CD; Enhancing FAO reverses pathogenic Trm cells." (PMID 41280910, 2025). "It has been reported that the AhR ligand I3C is capable of increasing PPARγ expression in a TNBS-induced colitis model, leading to disease remission mediated by control of inflammation exerted by IL-22." (PMID 39684781, 2024). "They concluded that EVOO-PE supplementation effectively mitigates experimental colitis through PPARγ up-regulation and inhibition of nuclear transcription factor-kappa B and MAPK signaling pathways." (PMID 39494333, 2024). "In a different animal study, treatment with pioglitazone (another PPARγ agonist) improved DSS-induced colitis, disease activity, and histology and decreased TNF-α secretion in mice in an annexin-A1-dependent manner." (PMID 39451206, 2024). "In patients diagnosed with inflammatory bowel disease (IBD); ulcerative colitis (UC), or Crohn’s disease (CD), as well as in experimentally induced colitis, the depressed PPARγ expression in colon epithelial cells has been shown." (PMID 39062500, 2024). "In another study, 5-ASA treatment in mice with DSS-induced colitis led to upregulated PPARγ expression in intestinal epithelial cells and reduced dysbiosis by Escherichia coli." (PMID 39451206, 2024). "In DSS-induced colitis, the agonist of PPARγ, luteolin, stimulating PPARγ reduced the expression levels of IL-1β and IL-6 and increased both the mouse Octn2 mRNA and protein expression." (PMID 38672410, 2024). "PPARG, expressed in various tissues, regulates lipid catabolism and exhibits anti-inflammatory effects when activated, potentially ameliorating colitis symptoms." (PMID 38835657, 2024). "According to previous research, hyperoside can improve DSS-induced colitis through MKRN1-mediated PPARγ signaling and Th17/Treg balance regulation." (PMID 39519671, 2024). "PPARγ agonists can improve inflammatory symptoms in mice colitis models, including DSS-induced mice colitis and T cell transfer-induced mice colitis models." (PMID 37554552, 2023). "In contrast, PPARγ signaling agonists, such as rosiglitazone, attenuate the severity of inflammatory lesions in both experimental and spontaneous models of colitis." (PMID 37118698, 2023). "In previous studies, it has been shown that PPARγ is highly expressed in the colon, and activation of PPARγ has a protective effect on colitis, while its expression is reduced in patients with UC." (PMID 36619196, 2022). "These transcriptome-wide impacts suggest that PPARα/γ dual agonist PAR5359 is superior in restoring colon homeostasis in C. rodentium-induced colitis than either PPARα or PPARγ agonist used alone." (PMID 35288651, 2022). "A recent study elegantly demonstrated the preventive effects of inosine on DSS-induced colitis through promoting A2AR/PPARγ-dependent mucosal barrier function." (PMID 36558471, 2022). "recently proposed a molecular mechanism for barley leaf protection against colitis by the gut microbiota-inosine-A2AR/PPARγ axis." (PMID 36466834, 2022).
colitis (continued). "Noteworthy, while the role of PPARγ in colitis has been investigated through numerous studies over the past 3 decades, the role of PPARα has been contradictory, and their dual agonism in IBD has never been explored." (PMID 35288651, 2022). "Overall, COS can improve colitis by regulating intestinal microbiota and the PPARγ/SIRT1-mediated NF-κB pathway." (PMID 35200626, 2022). "Treatment with β-glucans increased the production of IL-10 mediated by PPARγ, promoting the attenuation of colitis and elimination of C. glabrata." (PMID 35630457, 2022). "Highly interestingly, Moreira and colleagues demonstrated that CLAs, which are frequently used in dietary supplementation and known to activate PPARγ, have efficient anti-inflammatory effects that prevent colitis, but worsen colorectal cancer formation." (PMID 35954274, 2022). "Taken together, these findings indicate that PPARα/γ dual agonist PAR5359 is superior in ameliorating C. rodentium-induced colitis than either PPARα or PPARγ agonist used alone." (PMID 35288651, 2022). "Collectively, these findings indicate that BL protects against DSS-induced colitis possibly through activating the PPARγ signaling pathway." (PMID 33820558, 2021). "For the direct effect on immune cells, the triterpenoid fraction of C. asiatica, madecassic acid, were shown to promote differentiation of Tregs and attenuate dextran sulfate sodium-induced colitis in mice via regulating the PPARγ/AMPK/ACC1 pathway." (PMID 34479568, 2021). "Gliclazide attenuates acetic acid-induced colitis via the modulation of PPARG, NF-κB, and MAPK signaling pathways." (PMID 34992665, 2021). "For instance, troglitazone and rosiglitazone are the two PPARγ synthetic ligands that can dramatically reduce disease severity in experimental colitis models and in patients with ulcerative colitis." (PMID 33820558, 2021). "Out data thus reveal that inosine exerts the protective effects against colitis partly through A2AR/PPARγ signaling." (PMID 33820558, 2021). "Impaired intestinal mucosal integrity during colitis involves the peroxisome proliferator-activated receptor-γ (PPARγ), an important anti-inflammatory factor in intestinal mucosa homoeostasis, which is a potential target in colitis." (PMID 31989391, 2020). "In this study, MA can ameliorate experimental colitis through inhibiting the activation of γδT17 cells in a PPARγ-dependent manner." (PMID 32929062, 2020). "Since FXR and PPARγ are nuclear receptors known to abrogate colitis, we employed a TR‐FRET‐based ligand displacement assay (FXR) (Fig EV2G) and a cell line reporter assay (PPARγ) (Fig EV2H)." (PMID 32153125, 2020). "Further, significantly lower incidence of necrotizing enterocolitis (NEC)-like colitis has been reported in pups of n-3-PUFA supplemented mothers, associated with reduced IκBα/β levels and elevated PPARγ expression." (PMID 33603741, 2020). "Follow-up data showed that systematic administration of PPARγ agonist pioglitazone ameliorated the DSS-induced colitis and the development of colitis-associated hyperalgesia by repairing the intestinal mucosal barrier." (PMID 31989391, 2020). "As one of the first-line medications for the treatment of IBD, 5-aminosalicylic acid (5-ASA) activates peroxisome proliferator-activated receptor gamma (PPARγ) to attenuate colitis." (PMID 30804707, 2019). "Later, several studies using macrophage- or CD4+ cell-specific PPARγ KO mice revealed that the expression of PPARγ in macrophages or CD4+ T cells protects against colitis." (PMID 30804707, 2019). "It was reported that PPARγ played a satisfactory anti-inflammatory role in experimental colitis models." (PMID 31849652, 2019). "In the present study, C. glabrata overgrowth reduced IL-10 expression during the development of colitis, while β-glucan treatment increased IL-10 production via PPARγ sensing." (PMID 30524506, 2018).
colitis (continued). "β-glucan treatment increased IL-10 production via PPARγ sensing, promoting the attenuation of colitis and C. glabrata elimination." (PMID 30524506, 2018). "Madecassic acid exerted anti-colitis effect by restoring Th17/Treg balance via the PPARγ/AMPK/ACC1 pathway." (PMID 28358365, 2017). "In UC patients and experimental colitis models, the expression of PPARγ showed impaired features in colons; specific knockout of PPARγ in macrophages and epithelial cells of UC mice significantly aggravated the disease symptoms and pathological damages." (PMID 29375382, 2017). "In conclusion, madecassic acid was the active form of madecassoside in ameliorating colitis by restoring the Th17/Treg balance via regulating the PPARγ/AMPK/ACC1 pathway." (PMID 28358365, 2017). "Conversely, PPARγ synthetic agonists inhibit inflammation and reduce disease severity both in experimental models of colitis and in UC patients." (PMID 28928735, 2017). "In contrast, another study showed that PPARγ contributed to the development of colitis in a lymphopenic environment." (PMID 27335315, 2016). "In support of this, tissue specific knockout of PPARγ in the colon prevents the ability of CLA to protect against dextran sodium sulfate induced colitis." (PMID 26713087, 2015). "Selective epithelial ablation of PPARγ dramatically increased Lcn2 expression and its secretion after S. Typhimurium challenge, confirming the importance of epithelium-derived PPARγ in colitis." (PMID 24465207, 2014). "Since PPARγ is expressed in epithelial cells as well as in immune cells infiltrating colonic tissue during inflammation, the cell type that mainly contributes to PPARγ production during colitis remains a point of contention." (PMID 24465207, 2014). "Although PPARγ signaling controls various cellular processes during inflammation and pathogenesis, its regulation during S. Typhimurium-induced colitis remains unexplored." (PMID 24465207, 2014). "S. Typhimurium induced much more severe colitis in these mice, highlighting, for the first time, the importance of intestinal epithelium-derived PPARγ in protection against bacterial pathogenesis." (PMID 24465207, 2014). "This prediction was validated by results of adoptive transfer studies showing an increase of colonic iTreg and a decrease of Th17 cells in the gut mucosa of mice with colitis following pharmacological activation of PPARγ." (PMID 23592971, 2013). "PPARγ-agonists have been shown to ameliorate TNBS-induced colitis and the PPARγ ligand rosiglitazone has shown efficacy in mild to moderately active IBD." (PMID 23382912, 2013). "PRNP expression was increased both in submucosal inflammatory cells and to some degree also in epithelial cells, while a substantial down-regulation of PPARγ was evident in the epithelium after induction of colitis." (PMID 23382912, 2013). "Agonists of PPARγ have shown therapeutic efficacy in mouse models of colitis and clinical inflammatory bowel disease (IBD)." (PMID 23469071, 2013). "Our data indicate that T cell PPARγ prevents colitis and down-modulates effector T cell responses in mice with CDAD and suggest a potential crosstalk between miRNAs and the PPAR γ pathway." (PMID 23071818, 2012). "Oral treatment of C. difficile-infected mice with the PPARγ agonist pioglitazone ameliorated colitis and suppressed pro-inflammatory gene expression." (PMID 23071818, 2012). "Mesenteric adipose tissue from rodent colitis and Crohn's disease is metabolically active and shows inflammation-driven regulation of PPARγ, FXR and leptin." (PMID 21829567, 2011). "In mice, overexpression of PPARγ by an adenoviral construct in mucosal epithelial cells was associated with amelioration of experimental inflammation, and this study supports the hypothesis that the upregulation of PPARγ expression itself may have a protective effect against colitis." (PMID 20885923, 2010).